CD4 (CD4 molecule)
Diseases named in the same sentence as CD4 in open-access papers (continued):
Sharing a sentence is not in itself a finding about the gene and the disease.
infection (continued). "Consequently, while empirical evidence may be consistent with a positive association between multiple variant infection and faster CD4+ T cell decline, further investigation is required to establish a causal basis." (PMID 39471873, 2024). "To evaluate the reverse - if gorilla CD4 mutated to recapitulate the amino acids encoded in human CD4 may render the CD4 a better receptor for SIVcpz - we made and constructed cells expressing those CD4s and quantified the level of infection." (PMID 38014262, 2024). "Moreover, heterogeneity in functional T helper cell phenotype similarly influences HIV entry and infection susceptibility with CCR6 expressing CD4+ T cells, notably Th17 and potentially Th22 cells, being preferential targets of HIV infection in the bloodstream and mucosa of the FRT." (PMID 39872519, 2024). "In an experimental mouse model of cerebral ischemic stroke, lymphocyte loss may occur which reduces the number of CD4+T cells, resulting in cell apoptosis, while the delayed recovery of CD4+T cell count indicates an increase in the risk of subsequent infection." (PMID 38737099, 2024). "Therefore, the lower the number of helper T cells is, the lower the concentration of these immunoglobulins, probably due to a poor maternal B response to differentiation, which in turn predisposes HEU infants to a higher incidence of infection and hospitalization than mothers with low CD4 counts." (PMID 38375063, 2024). "Finally, the overall disruption of coordinated SARS-CoV-2-specific adaptive responses in older individuals, with a loss of coordination between CD4+ T cell and antibody responses, may contribute to a failure of infection control." (PMID 36776863, 2023). "JAK kinase inhibitors can inhibit the activation and differentiation of CD4 + T cells; reduce the number of Th1, Th17, and regulatory T cells (Tregs); inhibit the activation and maturation of NK cells; and easily cause immunosuppression, thus increasing the risk of infection." (PMID 37924363, 2023). "However, some studies emphasise that a role of TLR2 in HIV-1 disease progression rates (CD4+ 200 cells/μL) may be distinct from this gene’s impact on infection susceptibility." (PMID 36678440, 2023). "Despite a reliance on one’s current CD4 to risk stratify infection-associated risks in the clinical setting, our data suggest that nadir CD4, obtained years earlier and irrespective of current viral suppression or duration of ART, may be more immunologically relevant." (PMID 36805331, 2023). "Moreover, it also increases susceptibility to infection of CD4+ T cells." (PMID 35499323, 2022). "Yet, such an experimental infection of pigtailed macaques led to a surprising pattern of viral replication characteristic for short lived cells and a significant CD4+ T cell loss in the intestine and blood, in particular effector memory CD4+ T cells, and only a minimal monocyte depletion." (PMID 35154162, 2022). "However, the findings of the present study indicate that there are different expressions of TLRs, CD4, CD8b, and cytokines in these captive koala populations, which might be associated with different KoRV subtype infections." (PMID 36015032, 2022). "Importantly, HIV’s preference for cells expressing high levels of sialic acid was validated by demonstrating via sorting experiments that blood-derived memory CD4+ T cells expressing high levels of WGA were significantly more susceptible to infection than those expressing low levels of WGA." (PMID 35787792, 2022). "In summary, unvaccinated transplant patients with prior SARS-CoV-2 non-Omicron infection, or patients vaccinated with three doses of mRNA vaccine, may be at risk for symptomatic or severe omicron infection, owing to comparatively lower heterotypic antibody and CD4+ T-cell responses to Omicron BA." (PMID 35927279, 2022). "In addition, we evaluated whether any of the CAR/CXCR5+ cells were also vRNA+, given that the CD4+ CAR/CXCR5 are presumably susceptible to infection by SIV." (PMID 35130312, 2022).
infection (continued). "Second, we are considering only CD4+ T cells present in the peripheral blood, but other subsets of T cells present in lymphoid organs or tissues (like follicular T helper cells and Th17) are highly susceptible to infection and play a fundamental role in latency (101, –, 104)." (PMID 35499323, 2022). "Thus, we hypothesized that the propensity for CD4 T cells to die in the early phase of infection might be associated with weaker humoral responses against SARS-CoV-2." (PMID 36030261, 2022). "The loss of protective immunity observed when CD4+ T cell A.T. is delayed may be due to compromised T cell accumulation at the site of infection, or, if T cells are present, the ability of infected phagocytes to either elicit or respond to IFN-γ from these cells." (PMID 34543348, 2021). "The BKV usually causes asymptomatic infection in children; however, the virus is latent in the body, being reactivated in immunodeficient individuals, especially when there is depletion of cellular immunity when the presence of viral DNA is associated with depletion of CD4+ cells." (PMID 35528625, 2021). "The concomitant presence of high levels of CD4+ T-cell activation and a virus infecting and killing activated CD4+ T cells may help to sustain a vicious cycle, in which infection stimulates activation and activation stimulates infection, which may lead to a severe loss of CD4+ T cells." (PMID 33820568, 2021). "Although the overall frequency of HIV infection of CD4+ T cells is low—less than 1% in chronic infection—the cells that survive an infection (or their descendants) are not likely to carry an expressed provirus and are likely to remain highly susceptible to infection." (PMID 34696507, 2021). "Therefore, we hypothesized that infection with UgCl223 is associated with a protective TH1 CD4 T-cell response." (PMID 35186781, 2021). "This infection control could also be involved in the increased expression of genes associated with the activation of CD4+ T-lymphocytes, since both CMV surveillance and the continuous presence of pro-inflammatory cytokines in the environment may be continuously activating these lymphocytes." (PMID 34456907, 2021). "This could be explained by low CD4 count elicited dysfunction of the immune system and increased vulnerability of the host to infection, immunological deficiency that enhances the severity of the disease, and delayed recovery time and increase viral load across time." (PMID 33785009, 2021). "Finally, we assessed the kinetics of CD4+ T cell loss after SHIV.CH505 infection by flow cytometry." (PMID 33707443, 2021). "Furthermore, the substantial recovery of CD4 T cell counts in PLWH after SARS-CoV-2 clearance in wave 2 may be consistent with the Beta variant having more impact on the CD4 count relative to the ancestral SARS-CoV-2 strain infections in the first wave." (PMID 34608862, 2021). "In order to clarify the biological relevance and clinical importance of these findings, we investigated whether an increase in the CD4+ T cell level was caused by changes in the systemic inflammatory response (caused by surgery or infection) and if it was associated with their activation status." (PMID 35637935, 2021). "To explore whether IL-27 signalling was associated with changes in CD4+ T cell metabolism during infection, we first measured mitochondrial mass and membrane potential using MitoTracker dyes in WT and Il27ra-/- CD4+ T cells and Th1 cells 14 days after L. donovani infection." (PMID 33049000, 2020). "Interestingly, it has been found that during the acute phase of infection, Gal-1-deficient mice have a significantly decreased parasitic load and an increased count of pro-inflammatory cytokine-producing CD4+ T cells in the liver compared to infected wild-type mice." (PMID 32973776, 2020).
infection (continued). "Interestingly, in ART-suppressed infant SIV-infected RMs, treated at week 3 after infection, or here in RMs treated at week 6 post infection, the levels of cell-associated viral DNA were similar in CD4 T cells isolated from the different tissues such as blood, peripheral LNs, and the spleen." (PMID 31723251, 2020). "However, IL-4 produced by CD4+ T helper type 2 cells (Th2 cells) in Th2 responses inhibits Th1 responses and macrophage activation, which helps parasites survive and results in susceptibility of the host to severe infection." (PMID 32176727, 2020). "Additionally, in a study showing that immunization intravenously could protect mice against subcutaneous infection, this protection was mediated by CD4+ T cells and was associated with an increase in IFNγ production." (PMID 33291260, 2020). "We also found that immunized IL-10-deficient mice had improved bacterial clearance upon intraperitoneal infection with S. aureus, and importantly, protection induced by genetic deficiency of IL-10 could be transferred to naïve mice by the adoptive transfer of CD4+ T cells." (PMID 33291260, 2020). "The data suggest CD4+ T cells from lactating cows have an altered metabolic responsiveness that could impact the immunocompetence of these animals, particularly those in early lactation, and increase their susceptibility to infection." (PMID 32132555, 2020). "Moreover, selecting a cohort of HIV patients with high CD4 counts could reduce the risk of infections." (PMID 31680987, 2019). "Thus, it is likely that low amounts of CD4 on the cell surface of macrophages may greatly enhance infection by CD4-independent variants by augmenting virus binding or acting cooperatively to trigger conformational changes leading to fusion." (PMID 30415390, 2019). "Thus the diminished immune response, due to decreased proportion of CD4+ naïve T cells, may contribute to the risk of infection and mortality in PD patients." (PMID 31383007, 2019). "However, already early in the 1980's it became obvious that while the virulence of experimental trypanosomosis was not linked to the expression of a specific VSG variant, or the use of a specific MHC-II type, CD4+ T cells played an absolutely crucial role in infection control." (PMID 30333827, 2018). "Our study together has shed light on the molecular mechanisms underlying HSV-2-induced CD4+ T cell accumulation in mucosal infection sites, which may be crucial for understanding HSV-2 infection-enhanced HIV-1 sexual transmission and the development of intervention strategies." (PMID 30619292, 2018). "Therefore CD4+ T cell loss specifically rescued SG infection by M78- MCMV." (PMID 29447285, 2018). "Following acute infection, there is a brief recovery phase where there is some recovery of CD4+ T cells and a decrease of viral RNA, but then progressing into a persistent decrease of CD4+ T cells and increase of viral RNA associated with chronic stages of infection." (PMID 30728828, 2018). "Importantly, the increased levels of CD4+ T cell immune activation, IL-2 production, and cycling expression during acute infection were associated with less decline of CD4+ T cell after 2 years of infection." (PMID 29636753, 2018). "HIV target cells, including Langerhans cells, dendritic cells, CD4+ T cells and macrophages, exhibit wide distributions throughout penile epithelia and explanted (human) foreskin, glans and urethral tissues are susceptible to productive infection with CCR5-utilizing HIV ex vivo." (PMID 29584769, 2018). "This in combination with CD4+ T cell responses biased toward production of Th2-associated interleukins (IL) (IL-4, IL-5, and IL-13), may have exaggerated immunopathology upon later infection to RSV." (PMID 29552008, 2018).
infection (continued). "Similarly, the infection of replication-competent HIV-1NL4-3 in PHA-P-activated primary CD4+ T cells disrupted the association between SUN2 and lamin A/C, and the disassociation could be restored when HIV-1 replication was blocked with zidovudine (AZT)." (PMID 29717016, 2018). "However, CD4+ T cells from all PR and NP were susceptible to cis infection at a higher MOI (10−1)." (PMID 29643243, 2018). "Therefore, we were able to identify statistically significant associations between current infection and the proportion of certain CD4+ T cell populations circulating in the peripheral blood, but our study design does not allow us to infer causal relationships." (PMID 29505582, 2018). "Moreover, CD4+Foxp3+ cell-mediated suppression contributes to infection susceptibility." (PMID 30584243, 2018). "Therefore, an imbalance in the frequency and number of CD4+Foxp3+ cells, which is associated with the augmentation of Th1 effector cell function, has a deleterious effect on the magnitude of lung inflammation and, consequently, in the infection control." (PMID 30584243, 2018). "However, the exact role of NLRC3 and the mechanisms underlying its effects on CD4+ T cell activation and differentiation remain unclear, particularly during in vivo pathogen infection." (PMID 30133544, 2018). "Early after infection, adult macaques produce a high initial viral load at ~108 RNA copies per ml followed by a set point at ~105 viral copies per ml that corresponds to a loss in CD4+ T cell numbers in the blood, all of which resemble HIV infection kinetics in adult human patients." (PMID 29259605, 2017). "Furthermore, we demonstrated the high susceptibility of Il18r1−/− mice to infection with T. cruzi, which could be rescued by the adoptive transfer of WT CD4+ T cells." (PMID 28895840, 2017). "We favor two non-mutually exclusive explanations of this finding: the CD8α TM domain facilitates less HIV fusion than the CD4 TM domain, making cells less susceptible to CD4 CAR-mediated infection; and the CD8α TM domain promotes dimerization, which may potentiate signaling." (PMID 29023549, 2017). "Interestingly, the recombinant BCG vaccine VPM02 (ΔureC; hly+), which is more effective than the parental BCG in protecting against pulmonary tuberculosis in animal models, induces a balanced Th1/Th17 response and caused earlier recruitment of CD4+ T cells into the lungs after challenge infection." (PMID 29312343, 2017). "A decrease in the number or function of CD4 cells may cause recurrence, as in the case of patients receiving corticosteroids or chemotherapy, in transplant recipients, or in association with infection with HIV; in this scenario, a new therapeutic regimen may be required." (PMID 28649370, 2017). "However, CMV vaccination to prevent the formation of CD4+CD28null T cells and the adverse effects of the infection itself, could be beneficial for people at risk of developing MS." (PMID 28386103, 2017). "We therefore hypothesized that infection of placental macrophages would require variants with high CD4 affinity to scavenge the relatively scarce amounts of available CD4, and anticipated that envelope isolates from in utero-infected infants would thus be more sensitive to sCD4 inhibition." (PMID 28122636, 2017). "While CD4+ T cells have limited cytotoxic capacity, they can trigger apoptosis via tumor necrosis factor receptors and fas, activate myeloid cells to reduce their susceptibility to infection, and through cytokine signalling repress viral lytic gene expression directly." (PMID 28394921, 2017). "This disparity occurs because of the high rates at which CD4+ T cells traffic through the patch (with a mean residence time of about 10 hours), and because there is insufficient time to infect a large number of susceptible cells when within-patch bursts of infection are short lived." (PMID 27706164, 2016).
infection (continued). "Furthermore, activated CD4+ T cells are susceptible to infection, and increasing the pool of susceptible cells may favor reservoir reseeding, thus representing a key determinant of viral persistence." (PMID 26858716, 2016). "Consequently, alterations in the numbers or proportions of CD4+ T cell subsets may affect the capacity of antigen specific CD4+ T cell response to infections, leading to an increase in risk of infections in HEU children." (PMID 27165269, 2016). "However, the lack of concordance between residual viremia and viral variants driving de novo infection of CD4+ T cells on ART may reflect the predominance of defective plasma HIV RNA genomes." (PMID 27484989, 2016). "Importantly, selective deletion of Csf1 in CD4+ cells also resulted in significantly higher parasite burdens and delayed recovery from weight loss during the resolution phase of infection, directly demonstrating a role for MCSF derived from CD4+ cells in control of Plasmodium infection." (PMID 27923070, 2016). "However many studies found that massive infection of CD4+ T cells in GALT is directly associated with inflammation of the mucosal tissues and a breakdown of the mucosal integrity, resulting in microbial translocation from the lumen of the gut into peripheral blood." (PMID 26568963, 2015). "However, here we demonstrate that production of IL-10 by dermal CD4+ T cells occurs very early during the initial stages of S. mansoni infection, well in advance of egg deposition, which is a hallmark of chronic/long term infection." (PMID 25974019, 2015). "Likewise, mice genetically deficient in CD4+ or CD8+ T cell function were extremely susceptible to infection, and it was shown that T lymphocytes act by producing type 1 cytokines, such as IFNγ, and CD8+ T cell cytotoxicity mediated by perforin is important for resistance against infection." (PMID 25951312, 2015). "However, vvIBDV infection (Harbin-1 strain) caused serious pathological bursal lesions, and few lymphocytes could be collected to analyze the proportion of CD4+CD25+ cells." (PMID 25803101, 2015). "Merging both approaches would likely be even more effective, by coupling a method to prevent de novo infection in CD4+ cells susceptible to HIV infection with another that effectively inhibits viral replication in the small number of cells that may become infected with HIV, the virus after exposure." (PMID 24526828, 2014). "Whether these same CD4+ T-cell subsets are associated with infection is less clear." (PMID 25275464, 2014). "In our sample, males, younger people, people diagnosed in the provinces Guangxi, Henan, Heilongjiang, Jiangxi, Shanghai and Yunnan, and persons who acquired the infection through unknown transmission route showed a higher risk of low CD4 count at HIV diagnosis." (PMID 24024658, 2013). "The magnitude of the induced immune responses and the association between CD4+ T cells and protection from infection may depend on genetic variation between volunteers, particularly variation in class II MHC expression which is responsible for priming CD4+ T cells." (PMID 23613845, 2013). "In general, and in contrast to antigens solely associated with virus lytic infection (such as IE, gB and pp65), our results show that healthy seropositive donors have robust T cell responses to all the latency-associated antigens we analysed, which are dominated by CD4+ T cells." (PMID 24130479, 2013). "CD4+ T cells and DCs/LCs may still be some of the earliest cellular targets, but these cells likely do not dictate which variants circulating in the transmitting partner establishes a disseminated infection in the newly infected individual." (PMID 24369910, 2013). "Thus, in addition to neutralization sensitivity, a more restricted coreceptor utilization capacity may also serve to limit the emergence of CD4-independent variants during normal infection." (PMID 24219995, 2013).